ATRX (ATRX chromatin remodeler)
Diseases named in the same sentence as ATRX in open-access papers (continued):
Sharing a sentence is not in itself a finding about the gene and the disease.
Micropenis (1 paper, 2024). "Although all three present with micropenis, patient DSD-0115 with ATRX P1548L had right cryptorchidism, laterla hernia, and hyposmia, while DSD-0260 with both ATRX and AR variants didn’t show any other phenotypes in recorded." (PMID 39285472, 2024).
mismatch repair deficiency (1 paper, 2024).
nasopharyngeal carcinoma (1 paper, 2025). A carcinoma arising from the nasopharyngeal epithelium. "A loss of ATRX may contribute to a better prognosis in patients with nasopharyngeal carcinoma." (PMID 41472189, 2025).
neural tumors (1 paper, 2025). "Therefore, we explained the high incidence of ATRX mutations in mesenchymal and neural tumors with the fact that they both trigger ALT and impair differentiation, thus promoting two steps at once in the process of carcinogenesis." (PMID 40725011, 2025). "Since ALT is much more common in mesenchymal and neural tumors, research on the role of ATRX has been conducted almost solely in these tumor types." (PMID 40725011, 2025).
neurofibroma (1 paper, 2018). An intraneural or extraneural neoplasm arising from nerve tissues and neural sheaths. "Using this approach, we have demonstrated that 58% (43/74) of MPNSTs have aberrant ATRX expression (<80% nuclear expression) compared to only 7% (2/30) of benign (plexiform and atypical) neurofibromas." (PMID 29796169, 2018). "We then examined whether aberrant ATRX protein expression was also seen in plexiform and atypical neurofibromas, known precursor lesions to MPNSTs." (PMID 29796169, 2018). "Interestingly, only 7% (2/30) of plexiform neurofibromas and atypical neurofibromas show aberrant ATRX protein expression, compared to 57% (43/74) of MPNSTs showing aberrant ATRX protein (p < 0.0001, Fisher’s Exact Test)." (PMID 29796169, 2018). "Using IHC, we have demonstrated that 57% (43/74) of MPNSTs have aberrant ATRX expression compared to only 10% (2/21) of plexiform neurofibromas, and no (0/9) atypical neurofibromas, benign precursor lesions to MPNSTs." (PMID 29796169, 2018). "In summary, we demonstrate that ATRX is aberrantly expressed in the majority of NF1-MPNSTs, but not plexiform or atypical neurofibromas." (PMID 29796169, 2018).
osteoarthritis (1 paper, 2013). A noninflammatory degenerative joint disease occurring chiefly in older persons, characterized by degeneration of the articular cartilage, hypertrophy of bone at the margins and changes in the synovial membrane. "Since ATRX is highly expressed in chondrocytes, it could be a potential epigenetic regulator of specific genes involved in healthy cartilage maintenance and its loss may lead to diseases such as osteoarthritis." (PMID 24386478, 2013).
pancreatic ductal adenocarcinoma (1 paper, 2019). An infiltrating adenocarcinoma that arises from the epithelial cells of the pancreas. "These DEG expression patterns in PanNETs are quite different from that of pancreatic ductal adenocarcinoma and are related to A–D–M (ATRX–DAXX–MEN1) mutation." (PMID 31607839, 2019).
plexiform neurofibroma (1 paper, 2018). An elongated and multinodular neurofibroma, formed when the tumor involves either multiple trunks of a plexus or multiple fascicles of a large nerve, such as the sciatic. "In the current study, we analyzed ATRX expression by immunohistochemistry in 104 tumor samples (74 MPNST samples from both sporadic and NF1 patients as well as 21 plexiform neurofibromas and 9 atypical neurofibromas) from a total of 97 different patients." (PMID 29796169, 2018).
primitive neuroectodermal tumor (1 paper, 2024). A malignant neoplasm that originates in the neuroectoderm.
prostate (1 paper, 2025). "The precise roles of ATRX and DAXX in human prostate carcinogenesis remain incompletely understood, and further research is needed to clarify their potential clinical relevance." (PMID 41472189, 2025).
psychosis (1 paper, 2023). "However, to our knowledge we are the first to associate ATRX with risk for psychosis." (PMID 36624117, 2023).
skin cancer (1 paper, 2023). "We discovered that 7 of 11 IDH1-mutated tumours were also ATRX-mutated (28-fold enrichment compared to IDH1 WT skin cancers; p = 1.2 × 10−8, Fisher’s exact test) and that both ATRX and IDH1 were predominantly hit by somatic mutations (14 of 15 for ATRX, 7 of 11 for IDH1)." (PMID 36883553, 2023).
somatotroph tumors (1 paper, 2024). "Most PitNETs are without known mutations, with some exceptions: GNAS (somatotroph tumors), USP8 (corticotroph tumors), and ATRX (corticotroph tumors)." (PMID 39388031, 2024).
Spastic paraplegia (1 paper, 2006). Complete loss of the ability to move the lower limbs accompanied by spasticity of the lower limbs. "One report described a family with an ATRX mutation where affected members had spastic paraplegia from birth." (PMID 16722615, 2006).
spinal cord astrocytoma (1 paper, 2025). A low or high grade astrocytoma that arises in the spinal cord.
urinary bladder carcinoma (1 paper, 2025). "In men, alterations in DAXX and/or ATRX expression were reported for both prostate and urinary bladder carcinomas." (PMID 41472189, 2025). "To date, DAXX and ATRX immunohistochemistry have not been incorporated into routine molecular diagnostic panels for prostate or urinary bladder carcinomas in human oncology." (PMID 41472189, 2025). "Studies specifically assessing ATRX protein expression in urinary bladder carcinomas are currently lacking." (PMID 41472189, 2025).
urothelial carcinomas of the bladder (1 paper, 2025). "A loss of expression for DAXX and ATRX in human medicine is associated with a worse prognosis in PanNENs and urothelial bladder carcinomas." (PMID 41472189, 2025). "In contrast, urothelial carcinomas of the bladder displayed reduced expression of DAXX and ATRX in tumours with increased aggressiveness." (PMID 41472189, 2025).
Uterine leiomyoma (1 paper, 2021). The presence of a leiomyoma of the uterus. "In a cohort of variant uterine leiomyoma patient samples, 6% (9/142) showed ALT-relevant aberrations, such as ATRX/DAXX loss and/or ultra-bright telomeric foci." (PMID 34069193, 2021).
uterine tumors (1 paper, 2021). "Loss of ATRX in uterine tumors is a key difference between benign and malignant tumors." (PMID 33946962, 2021).
tumor (506 papers, 1999 to 2026). "ATRX mutation leads to decreased ATRX protein expression, and results in tumor genome instability, higher tumor mutation burden, and thus leading to increased sensitivity to chemotherapy, radiation therapy and immunotherapy agents." (PMID 40286729, 2025). "This diminished immune response was associated with accelerated tumor growth, suggesting a mechanism by which ATRX loss facilitates immune escape and drives tumor progression." (PMID 41228336, 2025). "We detected alterations in DAXX, MEN1, and ATRX, with mutations in the latter being only observed in samples extracted from primary tumor sites; these biomarkers have been shown to have prognostic significance in pancreatic NENs." (PMID 39825572, 2025). "The loss of DAXX and ATRX expression is associated with shorter patient survival and more aggressive tumour behaviour in PanNENs." (PMID 41472189, 2025). "Under IDH wild‐type conditions, ATRX mutation can accelerate tumor growth but simultaneously increase GBM sensitivity to treatment, resulting in a better prognosis for such patients." (PMID 40264576, 2025). "Compared to the ATRX mutation detected by IHC or NGS, the proportion of ATRX+ tumor cells based on mIHC has a more accurate predictive power for patient prognosis." (PMID 40264576, 2025). "In the context of IDH mutation, ATRX mutation can cause tumor cells to secrete various cytokine‐mediated inhibitory immune microenvironments and resist treatment." (PMID 40264576, 2025). "Downregulated proteins (PB DNA repair) included, for example, the ATRX, whose mutation in multiple cancers suggests a role in tumor induction and progression." (PMID 40727930, 2025). "We first analysed the prevalence of ATRX mutations in these subtypes and found an enrichment of ATRX alterations in iCMS3 tumours." (PMID 40468074, 2025). "For ATRX mutation, when the proportion of ATRX+ tumor cells is less than 37.0%, it can be detected as ATRX mutations, with an AUC of 64.0%." (PMID 40264576, 2025). "We also found a modest reduction in HNF4A and ATRX expression in liver metastases compared to their matched primary tumours, which provided further support for a progressive loss of colonic identity in advanced disease." (PMID 40468074, 2025). "The strongest expression of DLL3 was observed in a recurrent sparsely granulated silent corticotroph tumor that also had loss of ATRX." (PMID 40699376, 2025). "Recent studies have found that ATRX alterations contribute to immune escape and increased tumor growth in pleomorphic sarcoma and that ATRX-deficient tumor cells were particularly susceptible to the WEE1 inhibitor AZD1775." (PMID 40563612, 2025). "Among ALT tumors 9/20 (45%) harbored ATRX alterations and a single tumor (NBL49) a H3F3A missense mutation (p.A48E)." (PMID 39635126, 2024). "Other genes down-regulated in ATRX-altered tumours included USE1, SULT4A1 and the nuclear-encoded mitochondrial gene COX17." (PMID 38978571, 2024). "An inactivating ATRX variant was identified in the pituitary specimen of the ATRX-immunonegative tumor." (PMID 39108605, 2024). "As observed in G34-mutant pHGGs, ATRX mutations also occur in older pediatric patients (mean ages 11-17) suggestive of ATRX loss having an age specific influence on tumor progression." (PMID 38525424, 2024).
tumor (continued). "Subgroup analyses for PFS were subsequently performed for baseline clinicopathological features and the presence of MEN1, DAXX, and/or ATRX mutations (seen in 19 out of 31 patients with tumor NGS available, 61.29%)." (PMID 39272851, 2024). "The role of ATRX mutations in PanNETs is not well understood, but it is widely acknowledged that the simultaneous loss of multiple tumor suppressors is pivotal for PanNET development." (PMID 39479502, 2024). "GSEA of RCAS/Ntv-a tumors demonstrated differential engagement of cell cycle pathways in ATRX-deficient models relative to ATRX-intact counterparts, implicating tumor cell autonomous molecular mechanisms." (PMID 38272925, 2024). "IDH-A exhibits a greater incidence of ATRX loss, influencing the regulation of various chemokines, cytokines, and upstream transcription factors to sustain distinct tumor microenvironments." (PMID 39479502, 2024). "Immunohistochemistry was performed in the 11 available formalin-fixed paraffin blocks of tumor samples and showed that 9/11 tumors exhibited ATRX loss." (PMID 39233831, 2024). "In patients with supratentorial tumors, GTR (p = 0.040) and tumor size ≤24.0 cm3 (p = 0.004) indicated a better survival, while ATRX loss (p = 0.006) showed a worse prognosis." (PMID 38644565, 2024). "Tumors of the T2 subtype frequently harbored DAXX/ATRX mutations, as well as carrying 80% of mutations in the mTOR pathway genes, had a higher tumor mutation burden and longer telomeres, and presented a high frequency of alternative lengthening of telomeres." (PMID 39456803, 2024). "ATRX expression loss is linked to a telomere phenotype that is selectively prolonged, enabling tumor cells to evade planned cell death." (PMID 38818470, 2024). "ATRX staining for patient 4 tumor sample showed loss of nuclear ATRX in the tumor samples with faintly positive stromal cells serving as an internal control." (PMID 39351526, 2024). "Studies indicate that ATRX deficiency alters the tumor microenvironment by inducing innate immune responses to dsRNA, upregulating chemokines such as CCL2, CCL5, CXCL10 and IFNβ in innate immune pathways, and enhancing immune CD4+Tcell infiltration." (PMID 39479502, 2024). "ATP-dependent helicase ATRX was first reported in alpha thalassemia/mental retardation X-linked diseases in 1995, but its role in tumours remained unexplored until the last decade." (PMID 38126976, 2023). "ATRX, or α-thalassemia/mental retardation, X-linked, is a chromatin remodeling protein and tumor suppressor, with mutations or copy number alterations occurring in approximately 6% of the more than 65,163 tumors sequenced in the AACR GENIE database." (PMID 37200088, 2023). "Two ATRX-deficient tumors with high tumor mutational burden and mismatch repair deficiency were found." (PMID 37891325, 2023). "Patient LGS119 had two detected mutations (EPHA3 and ATRX) in her initial tumor, and these mutations were also detected in tumor samples obtained when the patient had a recurrence 17 months after the initial surgery." (PMID 36528667, 2022).
tumor (continued). "Very recently, a few studies have explored other tumor-promoting changes that occur in cancers with ATRX deficiency, including increased cellular motility in glioma cells and TGF-β activation with CDH1 (E-cadherin) downregulation in liver cancer cells." (PMID 36073547, 2022). "Our collective data suggest that ATRX loss provides a selective advantage to OS cells by reducing barriers to tumor initiation, increasing tumor growth rate, increasing migratory/invasive capacity, and enhancing survival in the metastatic niche." (PMID 36073547, 2022). "DAXX and ATRX function as tumor suppressors that are frequently mutated in ALT cancers, yet their precise role in regulating ALT is not fully elucidated." (PMID 36028493, 2022). "For instance, the presence of SDHB mutations, ATRX mutations, and telomerase inactivation have been correlated with the neoplasm’s metastatic potential or multifocal primary disease." (PMID 36010170, 2022). "The loss of expression of ATRX has been associated to the Alternative Lengthening of Telomeres phenotype, which allows tumor cells to escape programmed cell death." (PMID 35216305, 2022). "A splice site variant (c.4121-1G > T) was identified in ATRX, truncating the only copy of the known tumor suppressor located on chromosome X. Cytogenic analysis revealed no abnormalities in chromosome 3, but increase in copy number of 8q was detected." (PMID 35365243, 2022). "Given the role of ATRX loss in speeding the time to tumor initiation, we next sought to determine if ATRX loss would lead to increased tumor growth." (PMID 36073547, 2022). "Some studies have reported that DAXX/ATRX mutation is correlated with tumor stage and metastasis, and is associated with aggressive clinical behavior, reduced recurrence free survival (RFS) time, and worsening of the tumor-associated survival period." (PMID 36556070, 2022). "Here, we show that decreased ATRX expression is associated with more aggressive tumor cell phenotypes, including increased growth, migration, invasion, and metastasis." (PMID 36073547, 2022). "During treatment, mutations in the IDH1 and ATRX genes are used to determine the grade and aggressiveness of a tumour, whereas the MGMT status is used to determine if treatment with DNA alkylating agents such as TMZ would be worthwhile." (PMID 35681582, 2022). "PMMRDIA should be considered as a differential diagnosis in all cases of an IDH-mutant tumor with intact 1p/19q or loss of ATRX as a surrogate in a child, adolescent or young adult especially if histology shows high-grade features." (PMID 33216206, 2021). "The primary tumour harboured a C250T pTERT mutation and retained ATRX nuclear expression in tumour cells." (PMID 34573966, 2021). "By comparing phenotypic and genotypic features of the different tumour areas (i.e., pTERT mutation status and ATRX immunoreactivity) with the matched primary solid tumour, two cases showed evidence of intra-tumour heterogeneity." (PMID 34573966, 2021). "Human tumor studies have highlighted the pathological and prognostic significance of ATRX/DAXX mutations." (PMID 34680266, 2021). "The primary tumour showed a mild tumour infiltration and loss of ATRX expression in pTERT wild type tumour cells." (PMID 34573966, 2021). "Our analysis of mutation at observed G4 regions in ATRX-deficient tumors are the first to show the direct link between ATRX mutation and G4 in tumor samples by whole genome analysis, with C/G to A/T mutation being common in ATRX-deficient tumors." (PMID 34162889, 2021). "ATRX is a tumor suppressor that has been associated with protection from DNA replication stress, purportedly through resolution of difficult-to-replicate G-quadruplex (G4) DNA structures." (PMID 34162889, 2021).